MIR548A3 (microRNA 548a-3)
Synonyms: hsa-mir-548a-3; MIRN548A3
Gene: MicroRNA gene on chromosome 8 (104,484,369 to 104,484,465, reverse strand). Ensembl gene ENSG00000208032.
Gene Ontology:
Biological process: miRNA-mediated post-transcriptional gene silencing
Cellular component: RISC complex